G6PD (glucose-6-phosphate dehydrogenase)
Diseases named in the same sentence as G6PD in open-access papers (continued):
Sharing a sentence is not in itself a finding about the gene and the disease.
colorectal cancer (36 papers, 2010 to 2026). A primary or metastatic malignant neoplasm that affects the colon or rectum. "Other studies also found that high G6PD expression level was significantly associated with poor prognosis in bladder and colorectal cancers." (PMID 36313179, 2022). "Consistent with the present observations, previous study demonstrated that exposure of HCT116 human colorectal cancer cell to aspirin causes the acetylation of G6PD, and this is associated with a decrease in its enzyme activity." (PMID 33630390, 2021). "Mutations in the G6PD gene region in tumour tissues of patient A, colorectum carcinoma relapse." (PMID 20186333, 2010). "RRx-001, a G6PD inhibitor, has been under clinical investigation since 2011 for advanced malignancies, including colorectal cancer, lymphoma, and head and neck cancer, with promising outcomes." (PMID 39979245, 2025). "In patient-derived xenograft models, the silencing of G6PD can increase the sensitivity of colorectal cancer cells to oxaliplatin." (PMID 40685383, 2025). "Another study focused on Trx-1 and glucose-6-phosphate dehydrogenase (D6PD) in colorectal cancer, showing that the downregulation of Trx-1 inhibits EMT induced by glucose deprivation." (PMID 39201656, 2024). "Specifically, HIF-1α enhances glycolysis and PPP by regulating the expression of pyruvate kinase M2 (PKM2) and glucose-6-phosphate dehydrogenase (G6PD) to impart 5-fluorouracil resistance in colorectal cancer." (PMID 39343971, 2024). "The combined inhibition of Trx-1, G6PD, and glycolysis induces anti-tumor effects in colorectal cancer cells." (PMID 39201656, 2024). "circNOLC1 interacting with AZGP1 to activate mTOR/SREBP1 signaling, or sponging miR‐212‐5p to upregulate c‐Met expression, both of which can further induce G6PD to activate oxidative pentose phosphate pathway in colorectal cancer liver metastasis." (PMID 37870214, 2023). "To determine the role of the p52-ZER6/G6PD axis in tumorigenesis, we first analyzed the mRNA levels of p52-ZER6 and G6PD in clinical colorectal cancer tissues." (PMID 36977688, 2023). "As a result, mice injected with mutant Tyr112Phe-G6PD colorectal cancer cells developed significantly smaller tumours than their G6PD wild-type counterpart." (PMID 36217026, 2022). "Not only in bladder cancer, G6PD was also overexpressed in colorectal cancer (CRC) cells, and high expression correlated with poor prognosis and poor outcome of oxaliplatin-based first-line chemotherapy in patients with CRC." (PMID 33672990, 2021). "Inhibition of G6PD restores cisplatin sensitivity in ovarian cancer cells and enhances the sensitivity of colorectal cancer cells to oxaliplatin treatment." (PMID 29445340, 2018). "In this study, we mainly investigate the potential roles of G6PD in colorectal cancer (CRC) development and chemoresistance." (PMID 28692052, 2017). "Knocking out G6PD protects colorectal cancer cells from oxaliplatin-induced apoptosis." (PMID 40685383, 2025). "Additionally, AMF derived from DU145 prostate cancer cells has shown activity against colorectal cancer cells, primarily by downregulating glucose-6-phosphate dehydrogenase (G6PD) in the pentose phosphate pathway (PPP)." (PMID 39519266, 2024). "Together, these results showed that G6PD expression is overexpressed in colorectal cancer." (PMID 28692052, 2017). "Therefore, it is speculated that piRNA‐823 may promote the occurrence and development of colorectal cancer by enhancing the expression of downstream key molecule G6PD." (PMID 32596991, 2020). "In colorectal cancer, piR-823 fosters invasion by stabilizing HIF-1α and G6PD, correlating with poor prognosis." (PMID 42022287, 2026).
colorectal cancer (continued). "Collectively, quercetin demonstrates synergistic activity against colorectal cancer through concurrent suppression of inflammatory mediators (TNF-α→COX-2/iNOS axis) and oxidative effectors (LPO/NO/G6PD)." (PMID 40978482, 2025). "Here, we show that butyrate markedly inhibited glucose transport and glycolysis of colorectal cancer cells, through reducing the abundance of membrane GLUT1 and cytoplasmic G6PD, which was regulated by the GPR109a-AKT signaling pathway." (PMID 33855046, 2021). "Therefore, we speculated that piRNA‐823 may promote the occurrence and progression of colorectal cancer by enhancing the expression of downstream key molecule G6PD, which may be a key factor in the piRNA‐823 pathway to promote the progression of colorectal cancer." (PMID 32596991, 2020). "This study is the first exposition of the piR823/G6PD/HIF‐α regulatory pathway in colorectal cancer and will provide strong support for the development of piRNA‐823‐based gene therapy for colorectal cancer." (PMID 32596991, 2020). "Expression of both p52-ZER6 and G6PD was significantly upregulated in colorectal cancer tissues compared to adjacent non-cancerous tissues." (PMID 36977688, 2023). "Furthermore, in colorectal cancer, curcumin can modulate gene expression of HSPA5, SEC61B, G6PD, HMOX1, and PDE3B, affecting essential pathways like DNA replication or the cell cycle." (PMID 31744117, 2019).
COVID-19 (36 papers, 2020 to 2026). A disease caused by infection with severe acute respiratory syndrome coronavirus 2. "An ex vivo study from the same Asian population established that immune cells (monocytes) from G6PD patients were at a higher risk of viral infections and recent studies have linked G6PD deficiency with susceptibility to coronavirus (COVID-19)." (PMID 37340364, 2023). "It was predicted that COVID-19 would spread more widely in regions or countries with high incidence rates of G6PD enzyme deficiency, making the treatment and control of the COVID-19 outbreak more challenging." (PMID 37376524, 2023). "Further research in this area is warranted to validate these findings and establish strategies for early identification and management of patients with G6PD enzyme deficiency and COVID-19." (PMID 37376524, 2023). "The severity of COVID-19 is influenced by genetic variants in human G6PD, which are associated with impaired immune responses." (PMID 37376524, 2023). "Our previous study showed that G6PD-deficient individuals had a higher risk of COVID-19 infection, of COVID-19 hospitalization, and of developing long-COVID." (PMID 38068806, 2023). "DHEA can significantly inhibit G6PD enzyme activity, resulting in increased susceptibility to COVID-19." (PMID 36091812, 2022). "The seventh most frequent condition associated with COVID-19 in our literature search was glucose-6-phosphate dehydrogenase (G6PD) insufficiency." (PMID 35632654, 2022). "Further, it highlights that a deficiency of G6PD can be one of the genetic comorbid factors in the severity of COVID-19." (PMID 35880537, 2022). "While comparing the COVID-19 positive G6PD deficient with COVID-19 positive G6PD, normal activity showed that G6PD normal group had higher WBC, ANC, lymphocytes, eosinophils, and monocytes counts versus the G6PD deficient group." (PMID 36466438, 2022). "Dihydroartemisinin is a famous drug with phase 4 clinical trials for glucose-6-phosphate dehydrogenase (G-6-PD) deficiency and different infections, including COVID-19." (PMID 35935642, 2022). "Further, there is increasing evidence that SARS-CoV-2 enhances susceptibility to hemolytic triggers in G6PD deficient individuals, and conversely that G6PD deficiency is a predisposing factor for complications from COVID-19." (PMID 34543346, 2021). "The first article is a commentary which proposes glucose-6 phosphate dehydrogenase (G6PD) deficiency as a factor contributing to COVID-19 morbidity and mortality." (PMID 33117175, 2020). "A 13-year-old girl known to be glucose-6-phosphate dehydrogenase (G6PD) deficient was COVID-19 positive 20 days before the presentation." (PMID 33240687, 2020). "Moreover, the relatively small number of hospitalizations and deaths among G6PD-deficient individuals reduced the statistical power to detect associations with severe COVID-19 outcomes." (PMID 41433239, 2025). "Current research indicates that G6PD-deficient cells are more susceptible to human coronavirus infection than normal cells due to G6PD’s role in the metabolism of oxidative stress, which could increase COVID-19 mortality risk." (PMID 37376524, 2023). "Moreover, the physiological reaction of G6PD-deficient patients treated with remdesivir should be analyzed as to its use in treating COVID-19 patients expands." (PMID 36905446, 2023). "Despite the mentioned limitations, our study provides preliminary evidence of the relationship between G6PD and a higher susceptibility of contracting COVID-19 and may guide future research on the impact of COVID-19 on hematological and biochemical parameters." (PMID 37376524, 2023). "One of the health conditions that may increase the risk of death in people infected with COVID-19 is glucose-6-phosphate dehydrogenase (G6PD) enzyme deficiency, the most common enzyme deficiency in the world." (PMID 37376524, 2023).
COVID-19 (continued). "Moreover, it is consequently logical to think that G6PD-deficient patients are more prone to COVID-19-induced myocardial injury and other cardiovascular complications." (PMID 36905446, 2023). "Considering that SARS-CoV-2 is also a human coronavirus, DHEA may greatly increase the risk of COVID-19 due to its inhibition of G6PD." (PMID 36836216, 2023). "Impaired immune response against COVID-19 in G6PD-deficient patients." (PMID 36905446, 2023). "Moreover, we show limitations on COVID-19 treatment in G6PD-deficient individuals resulting from the pathophysiological background of the underlying disease." (PMID 36905446, 2023). "Current FDA recommendations suggest remdesivir as a treatment for COVID-19 patients; however, those with G6PD deficiency may exhibit more severe side effects than those with in-tact G6PD as a result of a decreased threshold for processing ROS in the liver." (PMID 36905446, 2023). "Because G6PD enzyme deficiency causes a redox imbalance in red blood cells, leading to hemolysis and tissue damage due to insufficient oxygen transport, COVID-19 may increase the risk of mortality in patients with G6PD enzyme deficiency." (PMID 37376524, 2023). "However, comparing the COVID-19 positive G6PD deficient with COVID-19 positive G6PD normal activity showed that G6PD normal group had higher WBC, ANC, lymphocytes, eosinophils, and monocytes counts versus the G6PD deficient group." (PMID 36466438, 2022). "Therefore, a deficiency of G6PD can lead to the dysregulation of ROS, which causes a severe inflammatory response in COVID-19 patients." (PMID 35880537, 2022). "Additionally, several diagnostic markers are altered in G6PD-deficient COVID-19 patients compared with G6PD wild-type COVID-19 patients." (PMID 35880537, 2022). "Deficiency of G6PD may be associated with severe COVID-19, since redox homeostasis mediated by this enzyme is involved in the immune response to viral infections." (PMID 35205026, 2022). "Among the several hypotheses regarding predisposition to develop severe symptoms during COVID-19, G6PD deficit has been considered." (PMID 33669011, 2021). "COVID-19 patients in Africa could experience adverse drug response when treated with chloroquine and hydroxychloroquine, since variants G6PD rs2230037 and CYP2C8 rs11572103 have considerable high AAF (26.7% and 18.9%, respectively)." (PMID 33312066, 2020). "Moreover, this study suggests that patients with G6PD enzyme deficiency may be at higher risk for severe COVID-19 outcomes." (PMID 37376524, 2023). "Recent research suggests that G6PD-deficient cells are susceptible to infection by human coronaviruses, as the G6PD enzyme is involved in the metabolism of oxidative stress, which may enhance COVID-19 mortality." (PMID 37376524, 2023). "In addition, G6PD deficiency can pose a challenge to surviving COVID-19." (PMID 35880537, 2022). "The high prevalence of variants in the G6PD gene found in this analysis suggests that it may be a significant interaction factor in clinical trials of chloroquine and hydroxychloroquine for treatment of COVID-19 in Africans." (PMID 34302047, 2021). "G6PD deficient individuals are at high risk of severe hemolysis when given anti-malarial drugs such as primaquine, quinine, other sulphonamide-containing medicines, and chloroquine, which has recently been shown to be potent for the treatment of coronavirus disease (COVID-19)." (PMID 32316233, 2020). "The administration of NAC (30,000 mg i.v. in 2 days) alleviated hemolysis and decreased COVID-19-associated increases in liver enzymes, C-reactive protein (CRP), and ferritin in the G6PD-deficient patient." (PMID 40141299, 2025). "For PT, the mean is higher in G6PD group compared to a G6PD with COVID-19 and COVID-19 groups (11.55 vs. 11.43 vs. 11.47)." (PMID 37376524, 2023). "For ALT, the mean is higher G6PD with COVID-19 (34.39) compared to other groups, while the standard deviation is increased in the G6PD group (44.28) compared to others." (PMID 37376524, 2023).
COVID-19 (continued). "A recent study examined the effect of COVID-19 on a group of G6PD patients, based only on the hematological parameters." (PMID 37376524, 2023). "In the second group of 21 COVID-19 patients with G6PD, tests were conducted on PT (47.62%), PTT (33.33%), fibrinogen (19.05%), total bilirubin (76.19%), ferritin (76.19%), aspartate aminotransferase (76.19%), and alanine aminotransferase (66.67%)." (PMID 37376524, 2023). "Additional study is required to validate our findings and to establish strategies for early detection and management of patients with G6PD and COVID-19." (PMID 37376524, 2023). "Certain case reports, mostly from areas with a low percentage of G6PD-deficient patients, mentioned the occurrence of hemolysis after HCQ treatment was initiated and urged caution when COVID-19 patients present with low hemoglobin." (PMID 35444908, 2022). "G6PD activity is essential for the adequate functioning of the antioxidant system and for innate immunity, which are needed to counteract COVID-19." (PMID 35805067, 2022). "A pilot study in patients with COVID-19 showed a significant increase in the levels of G6PD activity in red blood cells and it was concluded that the increase in G6PD was a compensatory mechanism against the viral infection." (PMID 35805067, 2022). "In addition, it is currently unknown how G6PD deficiency may affect COVID-19 disease progression." (PMID 34302047, 2021). "Indeed, ET would be another likely candidate, having demonstrated not only the ability to act as an antioxidant but also to protect against the various other pathological mechanisms of COVID-19 described in this review, and may be of greater benefit to G6PD-deficient individuals during COVID-19." (PMID 32646061, 2020). "G6PD testing before initiation of chloroquine is recommended in COVID-19 patients by NIH Coronavirus Disease 2019 (COVID-19) Treatment Guidelines." (PMID 33312066, 2020). "G6PD activity is essential for the adequate functioning of both the PO and AO components of the innate immune response to counteract COVID-19-induced immune dysregulation." (PMID 33195336, 2020). "In addition, this study showed that most G6PD patients with COVID-19 were below 15 years of age and a very low proportion of G6PD individuals with COVID-19 were above 80 years of age." (PMID 37376524, 2023). "When considering the findings of these studies and the potential of future research, physicians should be well-informed of the G6PD status of their COVID-19 infected patients, using remdesivir or other antiviral medication with great caution in positive patients, particularly those within class I." (PMID 36905446, 2023). "In D-dimer, the mean is higher in G6PD patients with COVID-19 (2.95) compared to other groups." (PMID 37376524, 2023). "In addition, there was an induction of the expression of 15 genes in autopsies from lungs obtained from obese patients with COVID-19, and among them the G6PD gene was found." (PMID 35805067, 2022). "In this review article, we summarize information on whether there is an increase or a decrease in the expression and/or activity of G6PD in COVID-19 patients and provide preliminary images supporting that there is an elevation in its expression." (PMID 35805067, 2022). "Therefore, the balance between antioxidant and pro-oxidant pathways mediated by G6PD plays a fundamental role in regulating physiological function during COVID-19." (PMID 35880537, 2022). "Comparing the COVID-19 negative G6PD deficient group with COVID-19 negative G6PD normal activity group showed lower Hb and hematocrit and higher bilirubin levels in the G6PD deficient group." (PMID 36466438, 2022). "Although ROS production by immune cells is required for the killing of COVID-19, but its activity could be neutralized by the enzymatic reactions of G6PD." (PMID 35880537, 2022). "Therefore, it is necessary to check the G6PD status of patients if CQ/HCQ is used to treat COVID-19." (PMID 36091812, 2022).